OR4C5 (olfactory receptor family 4 subfamily C member 5)
Description:
Odorant receptor.
Synonyms: OR4C5Q; OR4C5P
Tractability: Antibody: UniProt places it where antibodies can reach, with medium confidence; UniProt predicts a signal peptide or a membrane-spanning region; its Gene Ontology location is reachable by antibodies, with medium confidence.
Gene: Protein-coding gene on chromosome 11 (48,365,485 to 48,366,465, reverse strand). Ensembl gene ENSG00000176540.
Subcellular location: Cell membrane
Pathways (Reactome):
Sensory Perception: Expression and translocation of olfactory receptors
Gene Ontology:
Molecular function: olfactory receptor activity; G protein-coupled receptor activity
Biological process: detection of chemical stimulus involved in sensory perception of smell; G protein-coupled receptor signaling pathway
Cellular component: plasma membrane; membrane
Homologues: Orthologues: chimpanzee OR4C5 (94% identical), guinea pig OR4C5 (75% identical), rat Or4c35 (72% identical), mouse Or4c35 (71% identical), rabbit OR4C5 (70% identical). Paralogues in human: OR4C12 (59% identical), OR4C6 (58% identical), OR4C46 (57% identical), OR4C13 (57% identical), OR4C45 (57% identical), OR4A15 (56% identical), OR4A47 (56% identical), OR4C3 (56% identical), OR4A5 (53% identical), OR4B1 (53% identical), OR4C15 (53% identical), OR4S2 (52% identical), and 116 more.
Diseases named in the same sentence as OR4C5 in open-access papers:
OR4C5 is named in the same sentence as 4 diseases in open-access papers, as found by Europe PMC text mining. Sharing a sentence is not in itself a finding about the gene and the disease. The quoted sentences say what the papers report.
COVID-19 (1 paper, 2020). A disease caused by infection with severe acute respiratory syndrome coronavirus 2. "The analysis identified genes harboring deleterious mutations (according to the DANN score) with a statistically significant higher frequency in controls than in COVID-19 patients such as the olfactory receptor gene OR4C5 (adjusted p-value of 1.5E-10), and NDUFAF7, although to a lesser extent." (PMID 33206719, 2020).
lymphoma (1 paper, 2023). A malignant (clonal) proliferation of B- lymphocytes or T- lymphocytes which involves the lymph nodes, bone marrow and/or extranodal sites. "There was a significant SNP (18:41229735) within chromosome 18 within the olfactory receptor OR4C5, where the homozygous minor allele genotype (AA) was more common in lymphoma cases (45%) compared to carriers (22%) and controls (13%)." (PMID 37756103, 2023).
OR4C5 also shares sentences with these, for which no sentence is quoted: glioblastoma (1 paper); tumor (1).